VEGFA (vascular endothelial growth factor A)
Diseases named in the same sentence as VEGFA in open-access papers (continued):
Sharing a sentence is not in itself a finding about the gene and the disease.
hemangioma (88 papers, 2005 to 2025). A benign vascular lesion characterized by the formation of capillary-sized or cavernous vascular channels. "Studies on IHs show that corticosteroids inhibit the angiogenesis of infantile-hemangioma-derived stem cells by inhibiting vascular endothelial growth factor A (VEGF-A)." (PMID 40356783, 2025). "It has also been shown that propranolol inhibits the proliferation and induces the apoptosis of endothelial cells within hemangioma, which was mediated by the suppression of vascular endothelial growth factor A (VEGFA) expression." (PMID 37456875, 2023). "We further revealed the mechanism of action of the combinatorial treatment: β-elemene in combination with propranolol inhibits proliferation, migration, and angiogenesis of hemangioma by synergistically down-regulating the HIF-1-α/VEGFA signaling pathway." (PMID 37456875, 2023). "In the meanwhile, we detected the expression of VEGFA by qRT‐PCR in 20 pairs of fresh hemangiomas and corresponding paracancerous tissues, and found that it was significantly upregulated in hemangiomas." (PMID 32091151, 2020). "The effect of luteolin on VEGFA expression in DED is unknown, but luteolin can inhibit VEGFA expression in hemangioma-derived stem cells (HemSCs)." (PMID 36590763, 2022). "Therefore, our studies indicated that circAP2A2 can regulate the occurrence of hemangiomas through the circAP2A2/miR‐382‐5p/VEGFA axis." (PMID 32091151, 2020). "HIF-1α could inhibit VEGFA expression, whereas VEGF-mediated upregulation of IL-6 triggers the progression of hemangioma cells." (PMID 31949494, 2020). "Therefore, we explored whether miR‐382‐5p can play a role in the regulation of VEGFA expression in hemangiomas cells." (PMID 32091151, 2020). "Endothelial cell proliferation marks the active growth phase of a hemangioma, during which there is an overexpression of cytokines and angiogenesis-related molecules like fibroblast growth factor 2 (FGF-2), vascular endothelial growth factor A (VEGF-A), and matrix metalloproteinases." (PMID 39040727, 2024).
pulmonary hypertension (88 papers, 2006 to 2026). Increased pressure within the pulmonary circulation due to lung or heart disorder. "Similarly, omega-3 polyunsaturated fatty acid (PUFA ω-3) supplementation prevents BPD-associated pulmonary hypertension by reversing the reduced VEGFA and VEGF levels." (PMID 36769049, 2023). "Furthermore, hypoxia induces the phosphorylation of SerRS and promotes upregulation of VEGFA and remodeling of the pulmonary artery, which suggests that it is vital to correct hypoxia in controlling the progression of pulmonary hypertension in HUPRA syndrome." (PMID 36698945, 2022). "Due to lack of research, whether mutations of SARS2 result in pulmonary hypertension via VEGFA pathways remains unknown and deserves further research." (PMID 36698945, 2022). "First, the mechanistic roles of identified hub genes, including VEGFA, MDM2, and PTGS2, must be functionally assessed using both in vitro and in vivo pulmonary hypertension models." (PMID 41137320, 2025). "To test whether PIEZO1-mediated VEGFA production in neutrophils also plays a role in diseases characterized by disordered vascular homeostasis, we examine EC proliferation in WT and Piezo1-cKO mice exposed to LPS-induced acute lung injury or chronic hypoxia–induced pulmonary hypertension." (PMID 40454475, 2025). "Notably, vascular endothelial growth factor A emerged as a particularly intriguing and unanticipated differentially expressed gene, with its downregulation potentially representing a distinctive feature of IPAH among pulmonary hypertension subtypes." (PMID 41137320, 2025). "Notably, VEGFA emerged as a particularly intriguing and unanticipated differentially expressed gene, with its downregulation potentially representing a distinctive feature of IPAH among pulmonary hypertension subtypes." (PMID 41137320, 2025).
emphysema (87 papers, 2005 to 2025). "It is well established that loss of VEGFA activity in the lung can result in the development of emphysema." (PMID 21266048, 2011). "These cells are dependent on epithelial-derived VEGFA, and failure to specify these cells during development resulted in emphysema-like alveolar enlargement." (PMID 33239293, 2020). "Genetically modified MSCs (HSP-VEGFA-MSC) with cis-resveratrol (c-RSV)-induced HSP70 promoter-regulated VEGFA expression have been evaluated in elastase-induced pulmonary emphysema in mice." (PMID 29482654, 2018). "In experimental elastase-induced emphysema, BM-MSCs with cis-resveratrol-induced Hsp70 promoter-regulated VEGFA expression were infused and demonstrated to enhance lung function and levels of VEGF and anti-oxidant mediators (HO-1, Nrf2 and SOD), and reduced lung structural abnormalities." (PMID 37007034, 2023). "For instance, loss of endothelial markers vascular endothelial growth factor A (VEGF-A) and VEGFR2 in COPD is directly correlated to increase airflow obstruction, while restoration of the endothelium can ameliorate alveolar destruction in emphysema." (PMID 40966450, 2025).
myopia (86 papers, 2010 to 2026). "At the same time, only VEGFA and PlGF levels in patients with myopia were significantly less than emmetropes." (PMID 39597899, 2024). "Decreased retinal VEGFA concentration was found in marmosets with lens-induced myopia." (PMID 39607017, 2024). "One previous myopia study also found Bevacizumab could inhibit FDM chicks by about 50% through binding to VEGFA." (PMID 33946922, 2021). "Therefore, the increased level of Phosphatidate cytidylyltransferase 1 may prompt myopia via enhancing VEGFA signaling activity." (PMID 33946922, 2021). "From 137 eyes, VEGFA, VEGFC, and PlGF levels in patients with high myopia were significantly less than emmetropes." (PMID 39597899, 2024).
sarcoma (83 papers, 2001 to 2025). A usually aggressive malignant neoplasm of the soft tissue or bone. "Finally, a prognostic model for sarcoma patients was constructed using six hub genes: risk score = 0.05 × VEGFA + 0.25 × HMGB3 + 0.22 × FASN + 0.40 × RCC1 + 0.46 × NETO2-0.10 × BIRC5." (PMID 38240704, 2024). "For example, circFndc3b enhances the expression and signal transduction of vascular endothelial growth factor-A (VEGF-A) by interacting with RBP fused in sarcoma (FUS)." (PMID 38476331, 2024). "Among 19 IRGs enrolled in risk signature, VEGFA, CYR61, and RHOA have confirmed to be related to the pathogenesis or prognosis of sarcoma." (PMID 33557781, 2021). "Differential expression of VEGFA subtypes regulates sarcoma metastasis and response to anti-VEGFA." (PMID 33557781, 2021). "In our recent clinical trial, treatment with the vascular endothelial growth factor A (VEGF-A) antibody, bevacizumab, followed by a combination of bevacizumab and radiation led to near complete necrosis in nearly half of sarcomas." (PMID 22684860, 2013). "Vascular endothelial growth factor A (VEGFA) was a potent regulator that contributed to tumour growth and metastasis, while the isoform expression could be used to predict treatment outcome with bevacizumabin in sarcoma." (PMID 30464224, 2019).
geographic atrophy (82 papers, 2011 to 2025). "Furthermore, anti-VEGFA treatment may contribute to the progression of geographic atrophy due to insufficient vascularization or to the fact that VEGFA may serve as a vital survival factor for the retinal pigment epithelium (RPE)." (PMID 32312382, 2020). "Whereas therapies targeting vascular endothelial growth factor A (VEGFA) can suppress leakage, side-effects include vascular rarefaction and geographic atrophy." (PMID 32312382, 2020).
meningioma (82 papers, 2006 to 2025). A generally slow growing tumor attached to the dura mater. "Meningiomas are highly vascular tumors, with vascular endothelial growth factor-A (VEGF-A)-driven angiogenesis playing a central role in their progression, especially in recurrent malignant forms." (PMID 41246661, 2025). "We found that VEGFA mRNA expression was almost 3-fold higher in KLF4 meningiomas compared to AKT1 tumors, in agreement with previous studies." (PMID 36937440, 2023). "Mounting evidence suggests that secretion of vascular endothelial growth factor-A (VEGF-A) by meningioma cells induces angiogenesis and edemagenesis of tumoral as well as peritumoral brain tissue when a cerebral-pial blood supply exists." (PMID 34298854, 2021). "In order to verify the validity of our qRT-PCR methodology, we examined the mRNA levels of VEGFA between 14 meningiomas and 11 astrocytomas." (PMID 26580399, 2015). "Subsequent bars represented the different expression levels of VEGFA in normal brain, dura and meningiomas normalized by different reference genes." (PMID 21806841, 2011). "VEGFA and its VEGFR-1 receptor have been associated with regulation of the development of new blood vessels and peritumoral edema in brain tumors, a common feature in meningioma patients." (PMID 25965831, 2015). "Moreover, TRAF7 meningiomas express >5-fold higher levels of VEGFA compared to NF2 tumors, suggesting that VEGFA together with other DEGs from the RAP1 signaling pathway may be responsible for the secretory phenotype of KLF4 meningiomas." (PMID 36937440, 2023). "Considering the results of the normalization of VEGFA against every single reference genes with significantly altered results for CASC3 and IPO8, NormFinder displays a more accurate ranking for meningiomas and their control tissue." (PMID 21806841, 2011). "VEGFA is well known to be over-expressed in astrocytomas, but not meningiomas, and similar results would indeed serve as a "control group" for our methodology." (PMID 26580399, 2015). "Oedema in meningioma patients is postulated to be the product of vascular endothelial growth factor-A and is more frequently observed in invasive subtypes of meningioma, although this did not prove to be the case in our study (WHO grade I: 23.2% vs. WHO grades II/III: 28%)." (PMID 29959695, 2018).
triple-negative breast carcinoma (82 papers, 2011 to 2026). An invasive breast carcinoma which is negative for expression of estrogen receptor (ER), progesterone receptor (PR), and human epidermal growth factor receptor 2 (HER2). "Inhibition of VEGFA transcription significantly inhibited angiogenesis in triple negative breast cancer mice and improved the survival rate of mice." (PMID 40166052, 2025). "Vascular endothelial growth factor-A (VEGF) promotes vascular development and angiogenesis in 30–60% of triple-negative breast cancers after binding to VEGF receptor family member 2 (VEGFR)." (PMID 36678877, 2023). "Here, we aimed to find novel efficient antiangiogenic molecules targeting vascular endothelial growth factor A (VEGFA ) at the transcriptional level to treat triple-negative breast cancer (TNBC)." (PMID 32944400, 2020). "It has been reported to inhibit tumor-associated angiogenesis through the inhibition of ERK phosphorylation and to suppress VEGFA transcription and thus tumor angiogenesis in triple-negative breast cancer (TNBC), in addition to its antiproliferative and antimetastatic effects." (PMID 35956766, 2022). "Although we did not conduct a standalone study to assess the individual contributions of the EGFR, cMET, and VEGFA arms in one NSCLC xenograft model using inert arm comparator molecules, we performed such study in a triple-negative breast cancer (TNBC) model." (PMID 40452841, 2025). "We demonstrated that STAMBPL1 increased HIF1A transcription in a non-enzymatic manner, thereby activating the HIF1α/VEGFA signaling pathway to facilitate triple-negative breast cancer angiogenesis." (PMID 40208233, 2025). "Moreover, research indicates miR-5195-3p’s ability to restrain growth and boost chemosensitivity in triple-negative breast cancer, as well as its role in curbing proliferation and EMT, and enhancing apoptosis in NSCLC by focusing on VEGFA." (PMID 39390599, 2024).
Cognitive impairment (80 papers, 2011 to 2026). Abnormal cognition is characterized by deficits in thinking, reasoning, or remembering. "However, VEGFA is particularly protective in individuals at the highest risk of AD and cognitive impairment because elevated CSF VEGFA is associated with delayed hippocampal atrophy and cognitive decline in AD patients." (PMID 39857613, 2024). "Furthermore, recent investigations have demonstrated that hsa-mir-106a-5p which based on our results is linked to (TGFB1, ITGB1, and CXCR4), reduces the level of VEGFA, a protective factor against cognitive impairment in AD patients." (PMID 37705610, 2023). "Nevertheless, improvement in learning and memory after a bilateral carotid artery occlusion has been associated with an increase in VEGFA expression in the hippocampus, which suggests that VEGFA signaling could compensate for cognitive impairment." (PMID 35625687, 2022). "The ultimate goal was to identify a potential link between AUD-associated cognitive impairment and plasma levels of VEGFA and chemokines that might be eventually useful for clinical purposes." (PMID 35625687, 2022). "Thus, alcohol-induced alterations in chemokines and VEGFA might contribute to the neuroinflammation and cognitive impairment associated with AUD." (PMID 35625687, 2022). "The VEGFA/VEGFR signaling pathway activation alleviates cognitive impairment induced by chronic hypoperfusion." (PMID 40615465, 2025). "The relevance of the present study rests on the confirmation of the link between alcohol-induced dysfunctions in modulators of the blood–brain barrier (i.e., VEGFA) and neuroinflammation (i.e., chemokines) with the presence of cognitive impairment." (PMID 35625687, 2022). "However, recent studies have reported that hsa-mir-106a-5p decreased the level of VEGFA, which plays a protective role against cognitive impairment in AD patients, and its level is decreased in AD patients." (PMID 35326437, 2022). "Furthermore, the serum levels of ANG-2, VEGFA, haptoglobin, and p-Tau181 were correlated with cognitive impairment." (PMID 35769604, 2022). "VEGFA may exert a protective effect by preventing cognitive impairment." (PMID 40843367, 2025). "Moreover, higher VEGFA basal levels could predict positive treatment response and VEGFA levels decrease with the severity of illness and cognitive impairment in SZ." (PMID 36092733, 2022). "Indeed, a recent study proposes that vascular endothelial growth factor A (VEGFA) may mediate the effects of alcohol on cognitive impairment through blood–brain barrier permeability, facilitating the chemotactic infiltration (MIP-1α) of immune cells into the brain." (PMID 38535924, 2024). "To explore the influence of frontal cognition integrity on plasma concentrations of VEGFA and chemokines, we performed a Kruskal Wallis test with “frontal cognitive impairment” (no, mild, and severe) as a factor." (PMID 35625687, 2022).
lymphoma (78 papers, 2003 to 2025). A malignant (clonal) proliferation of B- lymphocytes or T- lymphocytes which involves the lymph nodes, bone marrow and/or extranodal sites. "Finally, CAFs mediated resistance to VEGF inhibitors in lymphoma xenografts models, by reactivating angiogenesis through platelet-derived growth factor C (PDGF-C) signaling, and PDGF-C targeting showed additive effects with anti-VEGFA antibodies." (PMID 36324182, 2022). "Vascular endothelial growth factor-A (VEGF-A), another positive downstream of NF-κB, promotes angiogenesis by activating its receptor VEGF-R1 in endothelial cells of micro vessels in lymphoma." (PMID 37274286, 2023). "Through the vascular endothelial growth factor A (VEGFA)/vascular endothelial growth factor receptor 1 (VEGFR1) axis, HIF-1α contributes to angiogenesis and promotes lymphoma cells to resist apoptosis." (PMID 34404434, 2021). "Increased circulatory IL-6 has been long established as a negative prognostic indicator in human lymphoma patients and simultaneous elevations of IL-6 and VEGFA are independent predictors of survival in aggressive NHL50,51." (PMID 40760075, 2025). "As a model gene we chose VEGFA, an important cancer gene that is expressed in many types of cancer, including lymphomas, and in ES cells, but not in differentiated white blood cells." (PMID 26886256, 2016). "However, high vascularity was found in the bone marrow of children with acute lymphoblastic leukemia and a positive correlation between the hemangiogenic protein Vascular Endothelial Growth Factor-A (VEGF-A) and lymphoma progression has been observed." (PMID 22404859, 2012).
squamous cell carcinoma (78 papers, 1998 to 2025). A carcinoma arising from squamous epithelial cells. "VEGFA is a target of miR-15b-5p also, which showed 2-10-fold reduction in expression in treated -104S cells and in chemotherapy-resistant squamous cell carcinoma." (PMID 24387052, 2014). "We analyzed subgroups according to the combinations of SLC2A1, VEGFA, APEX1, and HIF1A polymorphisms in patients with squamous cell carcinomas." (PMID 20540786, 2010). "Squamous cell carcinomas showed frequent genic amplification of CCND1 and SOX2 and/or TP63, while ERBB2, VEGFA, GATA4, and GATA6 were more commonly amplified in adenocarcinomas." (PMID 37893095, 2023). "The specific roles of VEGFA and ANGPT2 in adenocarcinoma (ADC) and squamous cell carcinoma (SQC) are still not fully understood." (PMID 31892982, 2020). "Squamous cell carcinomas showed frequent genomic amplifications of CCND1 and SOX2 and/or TP63, whereas ERBB2, VEGFA and GATA4 and GATA6 were more commonly amplified in adenocarcinomas." (PMID 28052061, 2017). "In particular, squamous cell carcinoma (SCC) of the skin, the second most common skin cancer in the general population, is characterized by invasive growth, pronounced angiogenesis and elevated levels of VEGFA." (PMID 23166713, 2012). "A different miRNA, miR-361-5p, represses a miRNA recognition element located in a conserved downstream region of the VEGFA 3′-UTR and is inversely correlated with VEGFA expression in human squamous cell carcinoma (SCC) cells and in healthy skin, indicating that it may play a role in cancers." (PMID 25197665, 2014). "Although it was not an independent prognostic factor for squamous cell carcinoma, the combination of NOTCH1 and VEGF-A (vascular endothelial growth factor A) expression levels did predict worse patient survival (n = 164)." (PMID 26491213, 2015).